SLC39A6 (solute carrier family 39 member 6)
Diseases named in the same sentence as SLC39A6 in open-access papers (continued):
Sharing a sentence is not in itself a finding about the gene and the disease.
cancer (44 papers, 2010 to 2025). A tumor composed of atypical neoplastic, often pleomorphic cells that invade other tissues. "In this study, we tried to find a cheaper and easier way to treat cancers which is directly linked to estrogenic hormones by preparing specific nanobody against the SLC39A6 protein." (PMID 35432806, 2021). "Overexpression of SLC39A6 has been related to the progression of several types of cancer, including breast, prostate, pancreatic, cervical and liver cancer." (PMID 34453638, 2021). "SLC39A6 was highly expressed in cancer tissues, but high expressed SLC39A6 was correlated with a favorable OS of LUAD patients." (PMID 33535184, 2021). "We further identified miR-192 as a metastasis suppressor of HCC and SLC39A6, which is an oncogene involved in different types of cancer, as a direct and functional target for miR-192 in HCC." (PMID 26684241, 2016). "The recent study indicated that LGALS3BP, MUC16, SCGN and SLC39A6 had abnormal expression in various cancer." (PMID 22438889, 2012). "Blocking SLC39A6 protein may result in reduced metastasis and proliferation in many malignant tumors." (PMID 35432806, 2021). "Two close homologues within this family, ZIP6 (SLC39A6, also known as LIV-1) and ZIP10 (SLC39A10), with a 43.5% sequence identity, are on the same clade of the ZIP family phylogenetic tree and have both been independently implicated in cancer." (PMID 32797246, 2021). "Furthermore, when the ESCC patients were stratified according to clinical stage, the survival rates of patients with SLC39A6 overexpression cancer were significantly lower than those of patients with SLC39A6 down-expression in early stage ESCC (P = 0.036)." (PMID 26444413, 2015). "Moreover, high SLC39A6 expression may alter zinc homeostasis in BC cells, which may in turn promote tumour cell metabolism and enable the development and progression of cancer." (PMID 34453638, 2021). "The findings suggested that the correlation of SLC39A6 and prognosis might vary in similar malignancies because of population heterogeneity, so whether it is elevated or suppressed in tumors is dependent on the types and contexts of cancers." (PMID 26444413, 2015). "In addition, most current studies demonstrated that SLC39A6, as an obligatory co-factor, has a crucial role in regulating epithelial–mesenchymal transition (EMT) in pancreatic and prostate cancers, causing cancer cell migration." (PMID 26444413, 2015). "Then, four zinc transporter genes—ZIP4 (SLC39A4), ZIP6 (SLC39A6), ZIP7 (SLC39A7), and ZIP10 (SLC39A10)—were selected based on their documented roles in cancer-related signalling pathways, such as MAPK, PI3K/AKT, and epithelial-to-mesenchymal transition (EMT)." (PMID 40869403, 2025). "SLC39A6 is also overexpressed in liver cancer and rewires mitochondrial energy metabolism by modulating the CREB1-PCK1 axis to provide energy for cancer cell motility." (PMID 41583444, 2025). "SLC39A4, 7, 10, 11 and 14 in cancer tissues were significantly highly expressed compared with in normal tissues.(P<0.05) But, expression of SLC39A6 and SLC39A8 were higher in normal samples than in cancer samples." (PMID 33535184, 2021). "SLC39A6 is essential for the nuclear localization of the zinc-finger protein SNAIL, a master regulator of cancer metastasis." (PMID 26684241, 2016). "In addition, SLC39A4 (ZIP4) and SLC39A6 (ZIP6) are involved in angiogenesis and EMT and promote cancer metastasis." (PMID 40362545, 2025). "We finally identified 4 mRNAs (AURKA, ASNS, ESR1 and SLC39A6), 3 miRNAs (has-let-7b-5p, has-mir-10a-5p and has-mir-17-5p), and 4 lncRNAs (SNHG16, CKMT2-AS1, NEAT1 and PSMA3-AS1), all of which have been reported in cancer." (PMID 36506097, 2022).
tumor (26 papers, 2007 to 2026). "High SLC39A6 mRNA and protein expression was associated with features characteristic of less aggressive tumours in the entire BC cohort and ER + subgroup." (PMID 34453638, 2021). "In METABRIC cohort, similar association was observed at the mRNA level, with high SLC39A6 expression was associated with low tumour grade (P < 0.0001 and P = 0.006) and good NPI scores (all P < 0.0001) in both the entire BC cohort and the ER + subgroup." (PMID 34453638, 2021). "Previous in vitro studies suggested that SLC39A6 is associated with progression in BC by facilitating zinc influx into tumour cells, which subsequently promotes tumour growth and the EMT." (PMID 34453638, 2021). "SLC39A6 CN gains were observed in 49/1980 (2.5%) of the entire cohort and 35/1471 (2.3%) of the ER + tumours, whereas 80/1980 (4.0%) of the entire cohort and 66/1440 (4.4%) of the ER + tumours exhibited CN loss, respectively." (PMID 34453638, 2021). "(1998) previously reported that in ER + tumours, SLC39A6 was associated with a variable response to endocrine therapy.This study indicates SLC39A6 is associated with a longer survival in ER + BC patients who did not receive hormone therapy more than who were given such treatment." (PMID 34453638, 2021). "Aberrant SLC39A6 expression in both ESCC tissues and ESCC cells suggests that increased SLC39A6 expression might be associated with tumor progression." (PMID 26444413, 2015). "This study also indicates that high cytoplasmic and high nuclear SLC39A6 protein expression and high SLC39A6 mRNA expression were associated with classical clinicopathological parameters characteristic of a less aggressive tumours and a better outcome, especially in the ER + subgroup." (PMID 34453638, 2021). "This study confirms that both high SLC39A6 mRNA and protein expression are observed more frequently in ER + tumours than ER-negative tumours." (PMID 34453638, 2021). "In recent years, it has been made clear that down-regulation of SLC39A6 significantly inhibits cell proliferation and reduces tumor growth." (PMID 35432806, 2021). "SLC39A6 CN gain was also associated with significantly poorer BCSS in the whole cohort and subgroup of ER + tumours (P < 0.0001 and P = 0.001, respectively)." (PMID 34453638, 2021). "The survival analysis and analysis of clinicopathological features in this study also suggest cytoplasmic and nuclear SLC39A6 exert distinct roles, especially in ER + tumours." (PMID 34453638, 2021). "In the current study, high cytoplasmic SLC39A6 protein expression, high nuclear SLC39A6 protein expression and high SLC39A6 mRNA expression were observed in 43%, 37% and 50% of the BC tumours overall, respectively." (PMID 34453638, 2021). "SLC39A6 immunoreactivity was observed in the cytoplasm and nuclei of the invasive epithelial tumour cells." (PMID 34453638, 2021). "We assessed the prognostic significance of oestrogen-regulated solute carrier family 39 member 6 (SLC39A6) in BC, with emphasis on ER + tumours." (PMID 34453638, 2021). "We also assessed the correlations between the expression of SLC39A6 and other well-characterised ER-related markers that have been identified as signature genes in ER + tumours, including FOXA1 and GATA3." (PMID 34453638, 2021). "Recent studies have determined SLC39A6 can be a good candidate for both tumor markers and antibody-drug conjugate (ADC) treatment." (PMID 35432806, 2021). "SLC39A6 protein was expressed at significantly higher levels in ER + tumours than ER-negative tumours (P < 0.0001)." (PMID 34453638, 2021). "To further evaluate the clinical significance of the miR-192/SLC39A6 axis in HCC, we determined miR-192 and SLC39A6 expression levels in another independent cohort of tumors and adjacent non-tumor tissues from 101 HCC patients." (PMID 26684241, 2016). "In conclusion, we newly determined that miR-192 targeted the SLC39A6/SNAIL pathway to reduce tumor metastasis in HCC cells." (PMID 26684241, 2016).
tumor (continued). "Increased expression of SLC39A6 was found to be closely correlated with histological grade and early Tumor-Node-Metastasis stage I/II." (PMID 26444413, 2015). "SLC39A6 is involved in maintaining the intracellular homeostasis of zinc, an ion that is essential for cell proliferation and tumor growth." (PMID 26444413, 2015). "However, in the luminal ER + tumours, high SLC39A6 nuclear expression was an independent predictor of longer BCSS (P = 0.034, HR 0.678, 95% CI 0.472‒0.972)." (PMID 34453638, 2021). "SLC39A6 may inhibit the ER in patients undergoing endocrine therapy, and also suggests that patients with ER + tumours expressing high levels of SLC39A6 may be candidate for a different type of endocrine treatment to further improve their outcome." (PMID 34453638, 2021). "High SLC39A6 mRNA expression was infrequent in the ER-negative tumours (21/449; 4%)." (PMID 34453638, 2021). "SLC39A6 protein expression was detected in the cytoplasm and nuclei of the tumour cells." (PMID 34453638, 2021). "Moreover, when the Cox regression model was restricted to ER + tumours and incorporated other ER-related proteins, nuclear SLC39A6 expression remained as the only independent prognostic factor for BCSS (P = 0.002)." (PMID 34453638, 2021). "We not only discovered that SLC39A6 could serve as an early detector of high-risk subjects and prognostic biomarker, but also discovered the tumor-promoting role of SLC39A6 in regulating ESCC progression and metastasis via inducing an EMT phenotype." (PMID 26444413, 2015). "Combined, our findings highlight a tumor-promoting role for SLC39A6 in ESCC, suggesting that SLC39A6 could serve as an early detector of high-risk subjects and prognostic biomarker." (PMID 26444413, 2015). "However, when endocrine therapy inhibits the ER functions, then the pro-proliferative/pro-EMT effects of SLC39A6 are restored and the association with a better outcome observed in the ER + tumours becomes not significant." (PMID 34453638, 2021). "SLC39A6 may have prognostic value in BC, especially in ER + tumours." (PMID 34453638, 2021). "SLC39A6 is up-regulated in pathological hormone-rich tissues, including breast and uterine cancer, where it is thought to be influenced by cellular inducement and may play an important role in tumor development and metastasis." (PMID 35432806, 2021). "High SLC39A6 mRNA expression (8.5 log fold-change or greater) was observed in 1207/1943 (62%) of the entire METABRIC cohort and in 1186/1473 of the ER + tumours (79%; P < 0.0001)." (PMID 34453638, 2021). "At the molecular level, only the solute carrier family 39, member 6 (SLC39A6) and secreted frizzle-related protein 1 (SFRP1) genes were significantly downregulated in M1S9-treated MDA-MB-231 tumor." (PMID 33007803, 2020). "Combined, our findings highlight a tumor-promoting role for SLC39A6 in ESCC and targeting SLC39A6 might be a potential therapeutic strategy." (PMID 26444413, 2015). "In METABRIC cohort, Similar results were obtained for SLC39A6 mRNA, as high SLC39A6 expression was associated with favourable BCSS in both the entire BC cohort and ER + tumours (P < 0.001 and P = 0.041), but not in ER- tumours (P > 0.05)." (PMID 34453638, 2021).
SLC39A6 also shares sentences with these, for which no sentence is quoted: diabetes (5 papers); colorectal cancer (3); esophageal squamous cell carcinoma (3); gastric adenocarcinoma (2); invasive breast carcinoma (2); Obesity (2); Zinc deficiency (2); acrodermatitis enteropathica (1); acute myeloid leukaemia (1); adenoma (1); anemia (1); asthenozoospermia (1); bladder cancer (1); colon cancers (1); glioblastoma (1); Hyperglycemia (1); Immunodeficiency (1); infection (1); lymph node metastasis (1); non-small cell lung carcinoma (1); prion disease (1); prostate tumor (1); renal cell carcinoma (1); stomach cancer (1); teratozoospermia (1); Type 2 Diabetes (1).